PTBP1 (polypyrimidine tract binding protein 1)
Diseases named in the same sentence as PTBP1 in open-access papers (continued):
Sharing a sentence is not in itself a finding about the gene and the disease.
tumor (continued). "Because PKM2 is a fundamental enzyme for regulation of aerobic glycolysis in tumor cells, we further determine that PTBP1 expression is positively correlated with aerobic glycolysis genes including LDHA, HK2, and ENO1." (PMID 32655719, 2020). "Recent studies indicate that CD154 has anti-tumor activity and growth-inhibitory effects and that PTBP1 is able to stabilize CD154 mRNA21,22." (PMID 31729427, 2019). "Together, our study is the first to reveal that circFOXP1 was upregulated in GBC and promoted the tumor progression in GBC cells by interacting with PTBP1 or sponging miR-370 targeting PKLR." (PMID 31623628, 2019). "CircFOXP1 interacted with PTBP1 or sponged miR-370, which promoted tumor progression and the Warburg effect in GBC by directly targeting the PKLR." (PMID 31623628, 2019). "The authors reported that this reduction in Myc expression, reduced GLUT1 and PKM2-Polypyrimidine tract binding protein 1 (PTB1) expression inhibiting tumor growth." (PMID 31288436, 2019). "A recent study showed that lncRNA-TRMP inhibits the translation of p27 by binding competitively with PTBP1 thus promoting the proliferation of tumor cells." (PMID 31221168, 2019). "Mechanistic studies confirmed that circFOXP1 exerted its tumor-promoting roles by modulating the Warburg effect through upregulation of PKLR expression by interacting with PTBP1, protecting PKLR from mRNA decay." (PMID 31623628, 2019). "These experiments suggest that knocking down PTBP1 suppresses the ability of senescent fibroblasts to promote tumor growth." (PMID 29990503, 2018). "Depletion of PTBP1 impaired the ability of irradiated fibroblasts to promote the growth of 5PT tumor cells in this setting." (PMID 29990503, 2018). "To assess the effect that depletion of PTBP1 in senescent hepatocytes has on tumor growth, we seeded the syngeneic tumor cells, and after 15 days evaluated the tumors macroscopically and by luciferase imaging." (PMID 29990503, 2018). "To investigate how PTBP1 depletion affects the tumor-promoting functions of the SASP, we used an experimental xenograft mouse model that monitors the effect of senescent fibroblasts on tumor growth." (PMID 29990503, 2018). "Knockdown of PTBP1 in senescent NRASG12V-expressing hepatocytes prevented the acceleration of tumor growth otherwise observed in senescent livers (NRASG12V_shRen) compared with non-senescent livers (NRASG12V, D38A)." (PMID 29990503, 2018). "Over-expression of PTBP1 or cortactin in mRNA levels and protein levels has been proved the relevance of tumor stage and prognosis in CRC previously." (PMID 28404950, 2017). "Inhibition of PTBP1 expression in CRC cells decreased tumor cell proliferation, migration and invasion." (PMID 28404950, 2017). "Our findings are consistent with previous results showing that PTBP1 is required for proliferation and that decreasing PTBP1 levels in tumor cells can result in greatly enhanced cell death." (PMID 27513449, 2016). "We previously demonstrated that PTBP1 depletion inhibits tumor growth, colony formation and invasiveness in vitro in ovarian tumor cells." (PMID 25079003, 2014). "The level of SIRT1 was low, while high amounts of BCL2, MDM2 and PTBP1 were noted in both types of tumours." (PMID 21655185, 2011). "EP300-AS1 knockdown promoted EBC1 tumor growth, while PTBP1 KO inhibited and abolished this effect." (PMID 40790019, 2025). "Moreover, mice injected with PTBP1-knockdown cells exhibited smaller and fewer tumor nodules in the liver, mesentery, and intestine than the control group." (PMID 40296916, 2025). "Moreover, a strong positive correlation was observed between PTBP1 expression and tumor grade, with significantly higher PTBP1 levels in Grade 1 and Grade 2 tumors compared to normal tissues in the CPTAC dataset." (PMID 41313521, 2025).
tumor (continued). "PTBP1, as an RNA‐binding protein, is involved in regulating various intracellular biological processes such as splicing, translation, stability, and localization of mRNAs and is extremely closely related to tumours." (PMID 40579921, 2025). "Both in vitro and in vivo functional assays confirmed the tumor-promoting role of PTBP1 in EC." (PMID 41313521, 2025). "In summary, in tumour cells, PTBP1 interacts with a variety of non‐coding RNAs to affect tumour progression and therapy, suggesting that PTBP1 may be one of the key factors coordinating the role of non‐coding RNAs." (PMID 40579921, 2025). "In addition, there are non‐coding RNAs that bind to PTBP1 to affect tumour progression through other ways." (PMID 40579921, 2025). "Furthermore, tumor weight was substantially lower in the PTBP1 knockdown group compared to the control group." (PMID 40296916, 2025). "PTBP1 is involved in various tumour‐related biological processes." (PMID 40579921, 2025). "For example, PTBP1 promotes malignant tumour progression by regulating variable splicing of ITSN1." (PMID 40579921, 2025). "Tumor volume was significantly reduced when PTBP1 was knocked down." (PMID 40296916, 2025). "Furthermore, PTBP1-mediated stabilization of ZMIZ1 has been shown to significantly accelerate tumor growth in vivo." (PMID 41019082, 2025). "Future studies may reveal the deeper functions of PTBP1 in different physiological and pathological states and provide more clues to understand its importance in tumour biology." (PMID 40579921, 2025). "In summary, based on the direct link between PTBP1 and tumour progression, this review provides a comprehensive analysis of the relevant studies on PTBP1 and tumours in recent years to elucidate the role of PTBP1 in tumours, the mechanism, and its clinical significance." (PMID 40579921, 2025). "As a carcinogenic circular RNA, CircSMARCAS may directly promote tumour formation through PTBP1‐mediated RNA stability regulation or signal transduction." (PMID 40579921, 2025). "Studies have shown that PTBP1 abnormalities can lead to tumours." (PMID 40579921, 2025). "Blocking the SNHG16/PTBP1 axis reduces tumor growth in 5-FU-resistant xenografts." (PMID 40977684, 2025). "Therefore, in this paper, we reviewed the structure and function of PTBP1, its role in various tumours, and key mechanisms of action." (PMID 40579921, 2025). "We demonstrate that PTBP1 is upregulated in EC and promotes tumor progression." (PMID 41313521, 2025). "Further studies on PTBP1 function may provide new targets and strategies for tumour diagnosis and treatment in the future." (PMID 40579921, 2025). "In summary, PTBP1 plays multiple roles in tumorigenesis and development, and its properties as an RNA‐binding protein enable it to influence the biological behaviour of tumour cells by regulating gene splicing and expression." (PMID 40579921, 2025). "Given the complex bidirectional relationship between lipid metabolism and ferroptosis in tumor cells, our findings suggest that PTBP1 may promote EC progression through regulation of ferroptosis." (PMID 41313521, 2025). "However, tumor regrew with PTBP1-untargeted cells in the end due to inadequate diffusion of ASOs throughout the entire tumor." (PMID 38662454, 2024). "Moreover, PTBP1 can repress the expression of autophagy-related genes (ATGs), thereby facilitating tumor growth and metastasis in colorectal cancer." (PMID 39366930, 2024). "Additionally, our study demonstrates that in situ delivery of PTBP1-ASOs successfully inhibited the growth of GSC tumor xenografts and prolonged survival in a mouse model." (PMID 38662454, 2024). "Our study thus suggests that PTBP1 may act as a potential novel therapeutic target for senescence-mediated tumor suppression." (PMID 39057099, 2024). "Furthermore, the spatial transcriptome analysis emphasized the distribution of PTBP1 expression throughout the tumor, with specific variations observed in certain clusters." (PMID 38918441, 2024).
tumor (continued). "Compared with WT group, PTBP1 Cas9-KO group had smaller tumor volume and weight." (PMID 37670313, 2023). "Initially, loss or gain of PTBP1 had no detrimental effects on the bodyweight of tumour-bearing mice." (PMID 36635500, 2023). "Inhibition of endogenous PTBP1 impeded the growth of xenografts as measured by tumour size." (PMID 36635500, 2023). "At the same time, PTBP1 was highly expressed in GC patients compared with other tumor types." (PMID 37670313, 2023). "PTBP1 has the biological function of alternative splicing, which can selectively splice Pre-mRNA, produce diversified mRNAs, transcriptional regulation of a variety of proteins, and mediate tumor cell survival, proliferation, metastasis and other processes." (PMID 37670313, 2023). "PTBP1 also showed a significant correlation with tumor purity of TNBC measured by ESTIMATE." (PMID 37900187, 2023). "In line with the previous results, targeting PTBP1 produced a 70% reduction in tumour weight." (PMID 36635500, 2023). "Moreover, the expression of c-Myc also attenuated the PTBP1 knockdown-mediated inhibitory effect of xenograft growth, as measured by tumour volume, tumour size, tumour weight, and fluorescence intensity of xenograft." (PMID 36635500, 2023). "Additionally, in vivo study showed that PTBP1 promoted tumor-initiating capacity reduced by TINCR depletion." (PMID 36385098, 2022). "Inhibition of PTBP1 blocks the tumor-promoting effect of SASP and impair immune surveillance." (PMID 36203873, 2022). "The starBase database was employed to examine the expression of miRNA-195-5p, while the Kaplan–Meier plotter, UALCAN, and Gene Expression Profiling Interactive Analysis (GEPIA) databases were utilized to analyze the tumor stage and prognostic value of miRNA and PTBP1." (PMID 35600383, 2022). "Notably, the expression level of PTBP1 was significantly positively correlated with tumor cell invasion." (PMID 36171198, 2022). "Finally, in vivo xenograft experiments validated that blocking the SNHG16-mediated miR-506-3p-PTBP1 axis effectively limited 5-Fu-resistant GC cell originated-xenograft tumor growth under 5-Fu treatments." (PMID 36447254, 2022). "The expression of PTBP1 in most tumor tissues was higher than that in normal tissues." (PMID 36595978, 2022). "Database prediction, RNA pull-down and RIP experiments suggested that linc01513 may play an anti-tumor effect by inhibiting PTBP1 protein level." (PMID 35003358, 2021). "PTBP1 increases the ratio of the PKM2/PKM1 variant by binding intron 8 of PKM and elevating the PKM2 transcript variant with exon 9 skipping, thereby enhancing the Warburg effect and promoting tumor progression." (PMID 34330892, 2021). "Here, the genes PTBP1, RNF114, XRN2 and ZNRD1 are described as associated with other neoplasms." (PMID 33057419, 2020). "This significant correlation between bone marrow infiltration and PTBP1 expression raises the possibility that PTBP1 may represent a biomarker that indirectly reflects tumor mass and the level of bone marrow invasion at diagnosis." (PMID 32655719, 2020). "Clinically, PTBP1 expression was present at all stages; it increased with disease progression and poor prognosis, which was even stronger elevated in patients with high tumor burden and drug resistance." (PMID 32655719, 2020). "In agreement with the tumor growth inhibition, the tumor weights were significantly increased when PTBP1 expression was knocked down, demonstrating the tumor suppressive effect of PTBP1 in vivo." (PMID 31729427, 2019). "Data show that knockdown of PTBP1 expression significantly enhanced CL1-5 tumor growth." (PMID 31729427, 2019). "The PTBP1’s regulatory function in RNA splicing is apparently needed for tumor cell growth." (PMID 31729427, 2019). "In addition, PTBP1 expression was significantly higher in normal tissues and tumor-adjacent tissues compared to tumor tissues." (PMID 31729427, 2019).
tumor (continued). "CD154 (the CD40 ligand) plays a role in anti-tumor activity and growth inhibitory effects in breast cancer and recent studies indicate that PTBP1 may stabilize CD154 mRNA via targeting its 3′-UTR21,22." (PMID 31729427, 2019). "One of our key findings was that PTBP1 depletion prevented the tumor-promoting effects of the SASP." (PMID 29990503, 2018). "Knockdown of PTBP1 in vivo reduced the pro-tumorigenic effects of senescence without increasing the risk of tumor initiation." (PMID 29990503, 2018). "This possibility is also compatible with the effect of PTBP1 on ES and tumor cell proliferation." (PMID 27513449, 2016). "PTBP1 regulates tumour progression through multiple mechanisms, including variable splicing, stability, subcellular localization, and translation, and the diversity of these mechanisms makes the role of PTBP1 in the tumour microenvironment increasingly complex." (PMID 40579921, 2025). "Therefore, targeting PTBP1 in dendritic cells can promote anti‐tumour immunity." (PMID 40579921, 2025). "In tumour therapy, PTBP1 may act as a key factor influencing targeted drug targets." (PMID 40579921, 2025). "Moreover, we discuss the difficulties and challenges faced in PTBP1 research and the clinical translational potential of PTBP1 research and summarise the future research direction of PTBP1 to provide new ideas for basic research and new directions for precision treatment of tumours in the clinic." (PMID 40579921, 2025). "The low expression of PTBP1 may indicates that the tumor cells are resting and various metabolisms are inactive; In contrast, the high expression of PTBP1 may present that the tumor cells are in an activated state, and tumor cells start to proliferate and evolve." (PMID 38918441, 2024). "However, more work is still being needed to translate basic research results into practical clinical applications, but in light of the progress of PTBP1 inhibitors in the field of neurology, there are great prospects for the development of PTBP1 inhibitors in the field of tumour therapy." (PMID 36635500, 2023). "In addition, PTBP1 is also involved in the development of multidrug resistance in tumours." (PMID 36635500, 2023). "Additionally, tumor-bearing studies demonstrated that PTBP1 knockdown could reduce tumor volume by fivefold after 28 days and increase the survival duration of transplanted mice compared to the control group." (PMID 35664063, 2022). "Knock-down of PTBP1 expression could enhance tumor growth in animal models." (PMID 31729427, 2019). "Indeed, over-expression of AXL may counteract the PTBP1-mediated apoptosis and knockdown of PTBP1 expression may increase tumor growth in vivo." (PMID 31729427, 2019). "Interestingly, knockdown of PTBP1 did not impart an increased risk of tumor formation, but rather resulted in increased survival and decreased tumor formation." (PMID 29990503, 2018). "The PTBP1 crosslinking and immunoprecipitation data recently generated by the ENCODE consortium confirmed the enriched binding of the protein downstream of CU-containing, KAPAC-predicted target PAS whose relative usage decreases in tumor compared to control samples." (PMID 29592812, 2018). "Similarly, miR-124-1 rs531564 GG genotype may promote miR-124 expression, which can directly suppress the expression of its targeting oncogene PTBP1, thus acting as a tumour suppressor." (PMID 28977965, 2017). "Furthermore, it has been shown that PTBP1 together with heterogeneous nuclear ribonucleoprotein A1/2 slicing factors are critical for the generation of pyruvate kinase M2 (PKM2) required for aerobic glycolysis in proliferating tumor cells." (PMID 27513449, 2016). "Therefore, the global effects of PTBP1 upregulation should be carefully assessed before PTBP1 could be considered a drug target to induce tumor-cell death." (PMID 24743263, 2014).
tumor (continued). "Luminescence signals in the lung region were significantly increased in the EP300-AS1 shRNA group, while PTBP1 KO inhibited and abolished EP300-AS1 knockdown-induced tumor metastasis." (PMID 40790019, 2025). "In this study, we investigated the anti-tumor mechanisms of curcumin in CRC and identified PTBP1 and CDK2 as critical downstream targets." (PMID 40469179, 2025). "The positive correlation between PTBP1 expression and immune infiltration in LGG and LIHC indicates a potential role for PTBP1 in modulating the tumor immune microenvironment." (PMID 38918441, 2024). "The result showed the number of tumor neo-antigens produced by LGG, UCEC, and STAD is positively correlated with the expression of PTBP1, and the opposite is true in THCA." (PMID 38918441, 2024). "To further explore the effect of PTBP1 expression on LGG patients, we divided tumor samples into high expression group and low expression group according to the average expression of PTBP1." (PMID 38918441, 2024). "To evaluate the expression profile of PTBP1 in GC patients, we performed immunohistochemical staining of PTBP1 on GC TMA containing 76 patient specimens, and 82 paired adjacent non-tumour tissues." (PMID 36635500, 2023). "All together, our data show that TINCR activates the transcription of ATG5 by interacting with PTBP1, leading to LCSC self-renewal and tumor propagation." (PMID 36385098, 2022). "We used the Cancer Genome Atlas (TCGA) to examine the expression levels of PTBP1, PTBP2, and PTBP3 in normal and tumor tissues, and cBioPortal was used to examine the genomic alterations." (PMID 36203873, 2022). "In line with a role of PTBP1 in CD19 mis-splicing in tumours, we find that patient samples from the TARGET B-ALL cohort on average show lower PTBP1 mRNA expression compared to healthy B cells." (PMID 36138008, 2022). "We first performed differentiation analysis and correlation analysis on the expression of the PTBP1, PTBP2, and PTBP3 genes in 30 tumor types using TCGA." (PMID 36203873, 2022). "GFP-PTBP1 restored the tumor volume and tumor weight reduced by PPP1R26-shRNA, revealing that overexpression of PTBP1 restores the tumorigenesis reduced by PPP1R26 depletion." (PMID 35292107, 2022). "As previously observed in vitro, pladienolide B administration in vivo significantly decreased various relevant tumor progression markers and critical oncogenic spliceosome components (VEGFA/EGFR/CDK4/PDGFRA/PDGFRB and SRSF3/PTBP1)." (PMID 35086552, 2022). "We found strong positive correlations of PTBP1 with Th2 cells, PTBP2 with T helper cells and Tcm, and PTBP3 with T helper cells, Tcm, and Th2 cells in most tumor types." (PMID 36203873, 2022). "The results showed that tumor tissue samples exhibit a significant up-regulation of MALAT1, PTBP1, and PSF in these databases, thus suggesting pathological relevance." (PMID 36563164, 2022). "PTBP1 and SLC39A1, which were overexpressed and indicated poor prognosis in LGG patients, were selected as tumor-specific antigens for LGG patients." (PMID 36307882, 2022). "S8, G to I), indicating that stable knockdown of MALAT1, PTBP1, and PSF effectively inhibited tumor growth in vivo." (PMID 36563164, 2022). "In the present study, we found that the expressions of both PTBP1 and PPP1R26 were upregulated in human HCC tumor tissues." (PMID 35292107, 2022). "In accordance with this notion, current data showed that an RNase T1 treatment, relative to the MALAT1 knockdown, exhibits more prominent influence on PTBP1/PSF interaction in HEK293 cells and in a series of tumor cells." (PMID 36563164, 2022). "The combination of polypyrimidine tract-binding protein 1 (PTBP1) and FLT3 messenger RNA enhances the translation efficiency of FLT3 kinase and participates in the proliferation and differentiation of tumor cells." (PMID 33880120, 2021).